MTOR (mechanistic target of rapamycin kinase)
Diseases named in the same sentence as MTOR in open-access papers (continued):
Sharing a sentence is not in itself a finding about the gene and the disease.
cancer (continued). "The ability of cancer cells to activate and upregulate any program of drug resistance which involves increased expression of proteins (e.g. drug efflux transporters) necessitates active protein translation and therefore PI3K/AKT/mTOR pathway engagement." (PMID 40360883, 2025). "Given the critical role of the PI3K/Akt/mTOR pathway in OSCC pathogenesis and its contribution to the aggressive characteristics of the tumor, targeting this pathway offers a strategic approach to cancer therapy." (PMID 39781358, 2025). "In addition to the PI3K/Akt/mTOR pathway inhibitors, histone deacetylase (HDAC) inhibitors have also been widely explored in cancer treatment." (PMID 41262902, 2025). "Further analysis of the KEGG and GO results for the top 20 differentially expressed genes revealed significant enrichment in cancer-related pathways, particularly the TGF-β, Foxo, and mTOR signaling pathways, all of which play key roles in cancer cell genesis, development, apoptosis, and metabolism." (PMID 41009525, 2025). "Furthermore, mTOR pathway inhibition, evidenced by reduced phosphorylation of AKT and S6K, occurred independently of AMPK activation, suggesting dual targeting of cancer survival pathways." (PMID 41398969, 2025). "Given that metabolic modifiers such as mTOR inhibitors and AMPK activators are already used therapeutically, elucidating these pathways could offer new strategies for cancer, infectious, and metabolic diseases." (PMID 41236793, 2025). "Module 2 appears to be more cancer-specific as it is consistently enriched for cell cycle pathways (“Cell cycle,” “Cellular senescence”), known cancer-related signaling pathways (“mTOR” and “JAK-STAT” signaling pathways), metabolic pathways, and cancer-specific disease terms." (PMID 41114645, 2025). "Additionally, miR-383 has been involved in several cancer pathways, such as the PI3K/AKT/mTOR pathway and the Wnt/β-catenin pathway." (PMID 40596133, 2025). "The effects of fasting on cancer are mediated by several key molecular pathways, including the IGF-1, mTOR, AMPK, and autophagy pathways, each of which plays a distinct role in regulating metabolism, cell growth, and survival under nutrient-deprived conditions." (PMID 39940361, 2025). "For instance, AKT protein levels, along with the phosphorylation of GSK3, mTOR, and S6K, are decreased in the skeletal muscle of cachectic cancer patients compared with their noncachectic counterparts." (PMID 39764565, 2025). "Curcumin can inhibit cancer progression through Akt/PI3K/mTOR signaling pathway; however, due to wide range of cancers and curcumin’s effects we were not able to mention all the studies and the section below is just giving some examples." (PMID 39906716, 2025). "Over-representation analysis (ORA) on the network nodes revealed significant over-representation of cancer-related KEGG signaling pathways, such as MAPK, Wnt, mTOR signaling, and PD-1 checkpoint, along with distinctly sex-biased pathways like the estrogen signaling pathway." (PMID 41024254, 2025). "Given these interactions between Notch and other cancer-related pathways, it is of great importance to study the combination therapies targeting Notch alongside PI3K/AKT/mTOR inhibitors, NF-κB deterrence, Her2/Neu targets, platinum-based chemotherapies, EGFR inhibitors, and Hh pathway suppressors." (PMID 40003637, 2025). "Furthermore, key molecular pathways under investigation comprise epithelial-mesenchymal transition (EMT), AKT, mTOR, PI3K, and Stat3 pathways, which represent critical nodes in the regulatory networks of cancer biology." (PMID 40771926, 2025).
cancer (continued). "While, generally, tRNA anticodon pools were found to be stable across human tissues, alterations in tRNA expression were observed across cancer types, mediated via activation of oncogenic pathways such as PI3K/AKT/mTOR, and MYC, which regulate RNA polymerase III-mediated tRNA expression." (PMID 41190243, 2025). "The possible apoptotic pathways for anti-cancer effects of curcumin on cell signal transduction include PI3K, Akt, mTOR, ERK5, AP-1, TGF-β, Wnt, β-catenin, Shh, PAK1, Rac1, STAT3, PPARγ, EBPα, NLRP3 inflammasome, p38MAPK, Nrf2, Notch-1, AMPK, TLR-4, and MyD-88." (PMID 41149437, 2025). "Additionally, the mTOR pathway can modulate NF-κB1 activity and influence COX2 expression, contributing to inflammation and cancer progression." (PMID 40938895, 2025). "In this paper, we systematically review the molecular basis of the inhibition of malignant tumors by ISO, including through the regulation of the cell cycle, PI3K/AKT/mTOR pathway, MAPK pathway, apoptosis/autophagy-related pathways, and the tumor microenvironment." (PMID 40507124, 2025). "Extensive research indicates that the AKT/mTOR and MAPK/ERK signaling pathways play crucial roles in the initiation and progression of malignant tumors, with their activation significantly enhancing cancer cell proliferation, invasion, and metastasis." (PMID 41234719, 2025). "The study by Yi (2020) revealed that modulating lipid synthesis via the PI3K-Akt-mTOR signaling pathway can suppress ferroptosis, presenting a novel therapeutic avenue for cancer treatment." (PMID 41210865, 2025). "In cancer cells, FASN overexpression promotes their survival and proliferation via the activation of HER1/2 and EGFR receptors, which in turn induce FASN expression via the activation of the MAPK and PI3K/Akt/mTOR pathways." (PMID 40723225, 2025). "miRNAs like miR-34a and miR-23a/b modulate upstream regulators of SREBP1 such as mTOR and AKT which have direct roles in cancer development and indirectly modulate lipogenesis by changing the activity of SREBP1, further integrating lipid metabolism with broader tumorigenic pathways." (PMID 40427160, 2025). "Unlike EGFR and HER2 inhibitors that target receptor tyrosine kinases located on the cell surface, ALK, BRAF/MEK, and PI3K/AKT/mTOR inhibitors act on non-receptor kinases in intracellular signaling pathways critical for cancer cell proliferation and survival." (PMID 40872476, 2025). "In the later stages, CIN II and CIN III, there was more enrichment in cancer-related signaling pathways, including transforming growth factor (TGF)-beta, mammalian target of rapamycin (mTOR), mitogen-activated protein kinase (MAPK), and RAS signaling as shown in a heatmap." (PMID 40109972, 2025). "In this study, the anti-cancer effect of FTO is consistent with its function as an m6A demethylase—low expression of FTO enhances the m6A modification of PDK1 mRNA, thereby stabilizing PDK1 and activating the pro-cancer AKT/mTOR pathway." (PMID 41145484, 2025). "In our study, the first patient received a suboptimal IS maintenance regimen after LTx, consisting only of steroids and mTOR inhibitor, which are commonly used as both anticancer treatment and IS maintenance regimen in SOT patients, especially after cancer diagnosis." (PMID 40168947, 2025). "OC had also been reported to inhibit mesenchymal-epithelial transition factor (c-MET) receptor tyrosine kinase and its downstream signaling pathways, reducing the activation of the mechanistic target of rapamycin (mTOR) levels, and suppressing COX-2 expression in different cancer types." (PMID 40807332, 2025).
cancer (continued). "By targeting specific molecular pathways involved in cancer progression, such as PI3K/AKT/mTOR, Notch, and Wnt, and leveraging immune responses with checkpoint inhibitors like PD-1/PD-L1 and CTLA-4, these therapies can halt tumor growth, reduce recurrence, and improve patient outcomes." (PMID 39949780, 2025). "Furthermore, in vitro experiments revealed that the effect of NEDD4L knockdown on cancer cell proliferation was reversed by treatment with rapamycin, a selective mTOR inhibitor that suppresses the AKT/mTOR signaling pathway." (PMID 40279519, 2025). "Impairment of ROBO signalling in cancer cells was shown to induce hyperactivation of mTORC1 and suppresses autophagy, which is consistent with reports that CA3 overexpression activates the mTOR pathway and inhibits autophagy." (PMID 41465490, 2025). "Moreover, there is a strong correlation between the activation of the PI3K/AKT/mTOR pathway and the acquisition of Epithelial‐Mesenchymal Transition (EMT) in cancer cells." (PMID 40717210, 2025). "Unsurprisingly, miRNAs have been shown to have important roles in cancer, regulating critical cancer-related cellular pathways (e.g., Myc, AKT, Wnt, Hippo, and mTOR) and exhibiting dual functionality as tumor suppressors or oncogenes depending on the target repertoire." (PMID 40239629, 2025). "Beyond transcriptional control, lncRNAs modulate key signaling pathways involved in cancer, including the PI3K/AKT/mTOR, Wnt/β-catenin, NF-κB, and TGF-β pathways, which play crucial roles in tumor proliferation, angiogenesis, epithelial-to-mesenchymal transition (EMT), and immune evasion." (PMID 40789840, 2025). "Moreover, ERO1 has been implicated in the activation of various signaling pathways, including PI3K-Akt/mTOR, S1PR1/STAT3, and Wnt/β-catenin, which are known to drive rapid cell proliferation and contribute to the Warburg effect in cancer." (PMID 40278350, 2025). "The link between POFUT1 and the PI3K/AKT/mTOR signaling pathway has not been really investigated in cancer." (PMID 40773107, 2025). "Moreover, the frequently dysregulated PI3K/Akt/mTOR pathway suppresses ferroptosis via SREBP-mediated lipogenesis; inhibiting this pathway sensitizes cancer cells to ferroptosis induction." (PMID 40732297, 2025). "Furthermore, CHRDL2 was found to differentially impact several key cancer pathways, including the EMT pathway, MYC, MTOR, PI3/AKT and RAF." (PMID 40434957, 2025). "Osthole, for example, inhibits cancer cell proliferation by arresting the cell cycle and inducing apoptosis, which may be related to modulation of the PI3K/Akt/mTOR pathway." (PMID 40430886, 2025). "Therefore, nanostructures have been introduced for the targeted cancer therapy and this section focuses on the specific regulation of PI3K/AKT/mTOR axis." (PMID 40740483, 2025). "CMTM4 KD reduced activation of EGFR/Akt/mTOR and NF-κB pathways, suggesting that different CMTM family members may have distinctly different functions in cancer cells." (PMID 39948411, 2025). "Calcium phosphate nanoparticles can silence PI3K/AKT/mTOR pathway components in cancer cells without harming them, making them intriguing gene therapy candidates." (PMID 40076496, 2025). "Therefore, the MAPK/ERK, Akt/mTOR, and PARP signaling pathways are promising therapeutic strategies for human cancers." (PMID 40123978, 2025). "For instance, disrupting crucial signaling pathways such as PI3K/AKT/mTOR or MAPK could, inadvertently, induce compensatory mechanisms within the cancer cells, potentially leading to more aggressive tumor behavior rather than promoting cell death." (PMID 40732251, 2025). "These modifications influence cancer cell survival strategies by regulating pathways such as PD‐L1/PD‐1 and mTOR/AKT, as well as the immune microenvironment (e.g., CD8+ T cell infiltration and Treg cells), which presents new possibilities for cancer immunotherapies." (PMID 39802639, 2025).
cancer (continued). "Additionally, research on SGLT-2 inhibitor drugs shows that they exert anti-tumor effects by modulating the AMPK/mTOR and HIF-1α pathways, providing a new perspective on the overlap between pathways in metabolic diseases and cancer." (PMID 41460830, 2025). "Therefore, it is suggested to utilize nanostructures for the delivery of small molecules in cancer therapy and suppression of PI3K/AKT/mTOR axis." (PMID 40740483, 2025). "Additionally, daidzin suppresses PI3K/Akt/mTOR pathway and TGF-β expression, effectively impeding EMT and reducing invasiveness in colon (SNU-C2A) and prostate (DU145, PC-3) cancers." (PMID 40620671, 2025). "To further explore whether the effects of NRG1 on BC cells are mediated by the AKT/mTOR pathway, we utilized the AKT inhibitor ARQ751 trihydrochloride to suppress AKT/mTOR signaling in cancer cells." (PMID 41213930, 2025). "Some cancers exhibit high mTOR pathway activity without canonical genetic alterations, suggesting multiple mechanisms of activation." (PMID 40647429, 2025). "Cancer cells with mutations in PI3K or lacking PTEN are not vulnerable to ferroptosis; however, blocking the PI3K/AKT/mTOR pathway can render them sensitive." (PMID 40740483, 2025). "This study provides the first evidence that pharmacological concentrations of VC induce the expression of pro-apoptotic proteins such as Apaf-1 and caspases -7 and -9, while inhibiting cancer cell survival proteins like Bcl-2, cyclins D and B1, CDK2, Akt, pI3K, and mTOR." (PMID 40149617, 2025). "In colorectal cancer (CRC), calycosin at the concentration of 50 μM induces cancer cells apoptosis and inhibits invasion by up-regulating and activating SIRT1 and AMPK, followed by inhibiting the Akt/mTOR signaling pathway in human colorectal (HT29) carcinoma cells." (PMID 41463300, 2025). "Targeting mTOR pathways, although effective in reducing tumor growth, does not present a suitable strategy for cancer prevention." (PMID 40427160, 2025). "In this specific tumor analysis, the mTOR inhibitor class of agents (via targeting AKT1 overexpression) scored the highest when compared to normal references with a Z-score of 3.7 and scored in the 96 percentile when compared to Cancer Reference Control (CRC)." (PMID 41560724, 2025). "The activation of the epidermal growth factor receptor (EGFR), a type of receptor tyrosine kinase that is overexpressed in GBM,99,100 results in the activation of multiple downstream signal transduction pathways related to cancer progression, including the PI3K/AKT/mTOR pathway." (PMID 40527011, 2025). "In addition, EZH2 can likewise take part in various molecular signaling pathways, like PI3K/Akt/mTOR and JAK2/STAT3, to promote the proliferation and migration of cancer cells." (PMID 41154714, 2025). "Furthermore, an additional layer of complexity in cancer metabolism regulation involves the interplay between AMP‐activated protein kinase (AMPK) and mTOR signaling pathways." (PMID 39969135, 2025). "In human papillary thyroid (B-CPAP) cancer cells subjected to 100 μM calycosin treatment, we see that activation of Sestrin2 (SESN2) and the subsequent up-regulation of p-AMPK and inhibition of p-mTOR, promoting cancer cell autophagy and apoptosis." (PMID 41463300, 2025). "Cancer cells in co‐culture with BJHTERT were more sensitive to MEK, PI3K, and mTOR inhibitors." (PMID 40411295, 2025). "Rapamycin-mediated mTOR inhibition sensitized FA− but not FA+ cells to rapamycin under nutrient stress, supporting a therapeutic metabolism-based vulnerability in FA− cancer cells." (PMID 40805278, 2025).
cancer (continued). "Among other important pathways and processes are apoptosis, HIF-1, mTOR, TNF, JAK-STAT, VEGF, and FoxO signaling, and pathways named after several cancer types and other diseases and infections (e.g. Epstein-Barr and Kaposi sarcoma-associated herpesvirus virus infections)." (PMID 40375077, 2025). "Given the relevance of this pathway in cancer biology, future studies should consider including PI3K/AKT/mTOR alterations to provide a more comprehensive understanding of the molecular mechanisms driving EOCRC, particularly among ethnic populations such as H/L patients." (PMID 40227607, 2025). "Additionally, metformin inhibits IGF‐1R autophosphorylation, reducing downstream PI3K/AKT/mTOR and MAPK pathway signaling, which limits cancer cell proliferation and survival." (PMID 40387523, 2025). "Additionally, phenothiazines promote mitophagy through the AMPK/mTOR/ULK1 pathway, enhancing autophagy and mitigating mitochondrial damage in cancer cells." (PMID 40718442, 2025). "Having said that dual PI3K-mTOR inhibitors have less toxicity and common symptoms of side effects like nausea, fatigue, vomiting etc., there are very limited dual PI3K/mTOR inhibitors that have advanced the clinical trials for cancer." (PMID 38584538, 2025). "Through gene set enrichment analysis (GSEA), we found that cancer-related pathways, including the TGF-beta signaling pathway, Wnt signaling pathway, mTOR signaling pathway, Hedgehog signaling pathway, and Notch signaling pathway, were enriched in TNBC with the CHD4-high phenotype." (PMID 38268032, 2024). "Cyclophosphamide is a widely utilized chemotherapeutic agent for pediatric cancers, known to elicit adverse effects, including perturbation of the PI3K/Akt/mTOR and Hippo signaling pathways, thereby diminishing ovarian reserve and fertility potential in females." (PMID 39702299, 2024). "Some of the reported mechanisms of action for CO on PC-3 and MCF-7 cancer cell lines are MAPK activation and inhibition of the PI3K/AKT/mTOR/S6K1 signaling pathway, signaling pathways that play an important role in cell proliferation, survival, and angiogenesis." (PMID 39769118, 2024). "Additionally, LINC01405 upregulation led to the increased cell populations, proliferation, and upregulation of critical cancer‐related genes, including AKT1, AKT3, mTOR, WNT3A, SMAD3, CYCLIN D1, CYCLIN D2, BCL2, and GSK3B." (PMID 38225865, 2024). "Aberrant activation of the phosphatidylinositol 3-kinase (PI3K)/AKT/mTOR signalling pathway has been identified as a key mechanism of resistance to treatment in cancer, including ET with or without a CDK4/6 inhibitor in MBC patients." (PMID 39322687, 2024). "In summary, we developed a pH-responsive drug delivery vehicle for receptor-selective drug delivery to cancer cells with high FRα expression and identified guidelines for selection of candidate PI3K/mTOR inhibitors for treatment of cancers sensitive to aberrant PI3K signaling inhibition." (PMID 40115434, 2024). "The activation of the PI3K/Akt/mTOR/p70S6K/4E-BP1 pathway by TGF-β significantly contributes to encouraging cellular changes that support EMT, a crucial process in the advancement and spreading of cancer." (PMID 38792249, 2024). "Several signaling pathways such as the PI3K/AKT/mTOR pathway, the Wnt/β-catenin pathway, the MAPK/ERK pathway, and JAT/STAT pathways are regulated by miRNAs in CC, further highlighting the importance of miRNAs in cancer development." (PMID 39263322, 2024). "Previous studies have shown that PDK1 can activate the PI3K/Akt/mTOR pathway to promote tumor proliferation and invasion; Additionally, phosphorylation of PDK1, an upstream regulator of C-Myc, activates PLK1-MYC signaling and promotes cancer proliferation." (PMID 38671369, 2024).